JPH2 (junctophilin 2)
Description:
[Junctophilin-2]: Membrane-binding protein that provides a structural bridge between the plasma membrane and the sarcoplasmic reticulum and is required for normal excitation-contraction coupling in cardiomyocytes. Provides a structural foundation for functional cross-talk between the cell surface and intracellular Ca(2+) release channels by maintaining the 12-15 nm gap between the sarcolemma and the sarcoplasmic reticulum membranes in the cardiac dyads (By similarity). Necessary for proper intracellular Ca(2+) signaling in cardiac myocytes via its involvement in ryanodine receptor-mediated calcium ion release (By similarity). Contributes to the construction of skeletal muscle triad junctions (By similarity). [Junctophilin-2 N-terminal fragment]: Transcription repressor required to safeguard against the deleterious effects of cardiac stress. Generated following cleavage of the Junctophilin-2 chain by calpain in response to cardiac stress in cardiomyocytes. Following cleavage and release from the membrane, translocates to the nucleus, binds DNA and represses expression of genes implicated in cell growth and differentiation, hypertrophy, inflammation and fibrosis. Modifies the transcription profile and thereby attenuates pathological remodeling in response to cardiac stress. Probably acts by competing with MEF2 transcription factors and TATA-binding proteins.
Synonyms: JP-2; JP2; CMD2E; CMH17
Tractability: Antibody: UniProt places it where antibodies can reach, with medium confidence; UniProt predicts a signal peptide or a membrane-spanning region; its Gene Ontology location is reachable by antibodies, with medium confidence. PROTAC: ubiquitination databases record sites on it.
Gene: Protein-coding gene on chromosome 20 (44,106,590 to 44,189,032, reverse strand). Ensembl gene ENSG00000149596.
Subcellular location: Cell membrane (Junctophilin-2); Sarcoplasmic reticulum membrane; Endoplasmic reticulum membrane; Nucleus (Junctophilin-2 N-terminal fragment)
Gene Ontology:
Molecular function: phosphatidic acid binding; phosphatidylinositol-3,4,5-trisphosphate binding; phosphatidylinositol-3,5-bisphosphate binding; phosphatidylinositol-3-phosphate binding; phosphatidylinositol-4,5-bisphosphate binding; phosphatidylinositol-4-phosphate binding; phosphatidylinositol-5-phosphate binding; phosphatidylserine binding; protein binding; DNA-binding transcription repressor activity, RNA polymerase II-specific
Biological process: calcium ion homeostasis; calcium ion transport into cytosol; regulation of cardiac muscle contraction by calcium ion signaling; regulation of release of sequestered calcium ion into cytosol by sarcoplasmic reticulum; negative regulation of transcription by RNA polymerase II; regulation of cardiac muscle tissue development
Cellular component: nucleus; endoplasmic reticulum membrane; junctional membrane complex; junctional sarcoplasmic reticulum membrane; plasma membrane; sarcoplasmic reticulum; sarcoplasmic reticulum membrane; membrane; Z disc
Genetic constraint (gnomAD): Loss-of-function variants: 38 observed, 47.4 expected, observed/expected ratio (o/e) 0.8, 90% interval 0.62 to 1.05. The synonymous counts are far from expectation, so gnomAD's model fits this gene poorly and the ratio says little. Missense variants: 964 observed, 894.82 expected, observed/expected ratio (o/e) 1.08, 90% interval 1.02 to 1.14. Synonymous variants: 480 observed, 393.4 expected, observed/expected ratio (o/e) 1.22, 90% interval 1.13 to 1.32.
Gene-disease validity (ClinGen):
ClinGen rates the evidence that JPH2 causes each of these diseases.
hypertrophic cardiomyopathy (autosomal dominant): Moderate. A condition in which the myocardium is hypertrophied without an obvious cause.
dilated cardiomyopathy (autosomal dominant): Limited. Cardiomyopathy which is characterized by dilation and contractile dysfunction of the left and right ventricles.
Homologues: Orthologues: chimpanzee JPH2 (99% identical), macaque JPH2 (98% identical), mouse Jph2 (87% identical), rat Jph2 (87% identical), dog JPH2 (83% identical), guinea pig JPH2 (68% identical), zebrafish jph2 (60% identical), Drosophila melanogaster jp (37% identical), Caenorhabditis elegans jph-1 (36% identical). Paralogues in human: JPH1 (50% identical), JPH3 (49% identical), JPH4 (38% identical).
Diseases named in the same sentence as JPH2 in open-access papers:
JPH2 is named in the same sentence as 39 diseases in open-access papers, as found by Europe PMC text mining. Sharing a sentence is not in itself a finding about the gene and the disease. The quoted sentences say what the papers report.
heart failure (30 papers, 2014 to 2025). Inability of the heart to pump blood at an adequate rate to meet tissue metabolic requirements. "Heart failure is commonly associated with downregulation of JPH2, and mutations in JPH2 can result in HCM." (PMID 37283586, 2023). "Downregulation of JPH2 gene has been associated with heart failure, and mutations in this gene are associated with HCM." (PMID 36357925, 2022). "Increasing evidence suggests down‐regulation of junctophilin‐2 contributes to T‐tubule remodelling, impaired cardiac contractility, loss of excitation‐contraction coupling and heart failure progression." (PMID 35048506, 2022). "Reduced JPH2 protein expression has been observed and causally linked to various inherited cardiomyopathies, pulmonary hypertension, and heart failure." (PMID 35001666, 2022). "Loss of JPH1 protein levels can cause skeletal myopathy, while loss of cardiac JPH2 levels causes heart failure and atrial fibrillation, among other disease." (PMID 35001666, 2022). "When combined with the striking phenotype observed in the 2 families presented here, which mimic these rodent models, our findings support the concept that loss of JPH2 expression can result in rapid progression of cardiomyopathy and heart failure." (PMID 31227780, 2019). "Downregulation of JPH2 gene has been associated with heart failure and mutations in this gene have been suggested to associate with HCM." (PMID 30235249, 2018). "It appears that JPH2 is similarly important for maintaining established dyads in adult cardiomyocytes, as JPH2 downregulation during heart failure has been linked to t-tubule remodeling [3, 54, 63•, 64, 86, 87]." (PMID 28447290, 2017). "In addition, activation of calpain by sustained [Ca2+]cyt elevation causes cleavage of Jph2, leading to T-tubule structural disruption and reduced efficiency of E-C coupling, promoting the progression of heart failure." (PMID 40551210, 2025). "Inherited mutations of JPH2 may cause hypertrophic or dilated cardiomyopathy, and loss of cardiac JPH2 levels may lead to heart failure and atrial fibrillation." (PMID 37744379, 2023). "JPH2 downregulation underlies the disruption of JMCs and T-tubules in cardiomyopathies and enhancing JPH2 expression is a promising therapeutic approach for the treatment of heart failure." (PMID 32053184, 2021). "Junctophilin cleavage was found to be dependent on the calcium-activated protease calpain, as administering a calpain inhibitor to an inducible mouse model of heart failure blocked JPH2 cleavage and the associated t-tubule disruption and abnormal calcium handling." (PMID 34305529, 2021). "Furthermore, induction of JPH2 expression silencing in adult mice is associated with rapid deterioration into heart failure with a dilated left ventricle and loss of systolic function." (PMID 31227780, 2019). "That this function is essential was demonstrated by studies showing that genetic knockout of Jph2 is embryonic-lethal due to heart failure resulting from impaired EC coupling and that acute knockdown of Jph2 expression in cardiomyocytes in vivo causes heart failure and death." (PMID 31591206, 2019). "For example, expression of JPH2 in the heart is decreased in animal models of dilated cardiomyopathy and hypertrophic cardiomyopathy associated with heart failure, and point mutations in JPH2 are associated with hypertrophic cardiomyopathy (34, –36) and arrhythmias in human patients." (PMID 31591206, 2019). "Thus, the primary role of Mg29 in the heart appears to be t-tubule stabilization to partially counter the loss of native anchoring proteins such as Jph2 during heart failure." (PMID 28706255, 2017). "Activation of calpain by sustained [Ca2+]cyt elevation is involved in T-tubule disruption (as occur in progressive heart failure) via cleavage of junctophilin 2 (Jph2) and activation of CaN by cleavage of the AID." (PMID 40551210, 2025).
heart failure (continued). "Cardiac-specific knockdown of Jph2 leads to heart failure, reduced CICR, and abnormally increased RyR2 activity." (PMID 40551210, 2025). "In light of our numerous prior investigations of the potential therapeutic role of THs in heart failure, we focused this study on the effects of T3 on Jph2 localization with RyR2 clusters and organization within the dyad using a TH-deficient disease model." (PMID 39365674, 2024). "Calpains 1 and 2 activate in heart muscle damaged by ischemia or in conditions of heart failure, to proteolyze JPh2." (PMID 36724092, 2023). "A further mechanistic study revealed that a cardiac ablation of the RBFox2 protein resulted in transcriptionally induced miRNAs in combination with enhanced miRNAs targeting Jph2, which directly contributed to heart failure." (PMID 36674797, 2023). "Cardiomyocyte-restricted tamoxifen-inducible short hairpin RNA (shRNA)-mediated JPH2 knockdown resulted in rapid-onset severe heart failure and increased mortality within 1 wk in adult mice." (PMID 35001666, 2022). "The 3D contextual information it has provided us in terms of t-tubule geometries, organization of structural proteins such as JPH2, and examining RyR cluster fragmentation in heart failure has been pivotal to our observation of JPH2 sub-domains." (PMID 36189802, 2022). "Protein expression levels of JPH2 were found to be reduced in patients with ischemic heart failure and a rat model of decompensated heart failure." (PMID 35001666, 2022). "The reduction of JPH2 downregulation was found to correlate with the severity of systolic heart failure." (PMID 35001666, 2022). "Nevertheless, it has been demonstrated that the cleavage of junctophilin-2 by calpain releases an N-terminal peptide, which can translocate to the nucleus and ultimately has a protective effect against heart failure." (PMID 34307509, 2021). "In an inducible mouse heart failure model, where JPH2 undergoes proteolytic cleavage, t-tubules are disrupted, suggesting that intact JPH2 is required for t-tubule maintenance." (PMID 34305529, 2021). "In a mouse model of heart failure, the 97 kDa full length Jph2 protein was shown to be cleaved by calpain, a calcium-dependent protease, thus liberating a 75 kDa amino-terminal (NT)-fragment." (PMID 31810440, 2019). "In this study, we identify two Iranian families hosting a novel loss-of-function (LOF) JPH2 variant that, when homozygous, was associated with DCM and death in early childhood from cardiac failure." (PMID 31227780, 2019). "Inducible cardiac-specific Jph2 knockdown in mice leads to ventricular dilatation, postnatal heart failure and increased mortality." (PMID 29208631, 2018). "As there is now considerable evidence linking JPH2 downregulation to impaired Ca2+ homeostasis and arrhythmia in heart failure, this protein is considered to be a promising therapeutic target." (PMID 28447290, 2017). "The precise mechanisms responsible for promoting JPH2 downregulation during heart failure continue to be examined." (PMID 28447290, 2017). "Junctophilin-2 decreased in cardiac diseases such as hypertrophic cardiomyopathy, dilated cardiomyopathy and heart failure, thus contributing to defective excitation-contraction coupling." (PMID 24945867, 2014). "The possible mechanism was that the prolonged incubation of ISO induced NRCMs to develop a severe dysfunction resembling a heart failure phenotype, which depressed RBFox2 and led to the repression of its downstream protein Jph2, and then eventually impaired cardiac E–C coupling." (PMID 36674797, 2023). "Frayed RyR patterns observed adjacent to these constitute new evidence that the destabilization of the RyR arrays inside the JPH2 sub-domains may seed the primordial foci of dyad remodelling observed in heart failure." (PMID 36189802, 2022). "Inducing JPH2 knockdown led to an increased frequency of heart failure events." (PMID 35053257, 2022).
heart failure (continued). "Jph2 null mice die during the early embryonic development, as a result of cardiac failure." (PMID 29208631, 2018). "An important role of JPH2 reduction in disease pathophysiology is supported by the observation that overexpression of this dyadic anchor protects against t-tubule degradation and heart failure development." (PMID 30618792, 2018). "Furthermore, JPH2 knockdown prevents full t-tubule maturation, leading to heart failure in developing mice." (PMID 28447290, 2017). "Indeed, our results suggest that the effects of Mg29 are only uncovered in heart failure models where Jph2 is downregulated." (PMID 28706255, 2017). "A recent study also showed that calpain-2 cleaves junctophilin-2 in heart failure and that the C-terminal fragment of junctophilin-2 generated by calpain-2 translocates to the cardiomyocyte nucleus, which may promote isoproterenol-induced hypertrophy in cardiomyocytes." (PMID 34440793, 2021). "This notable work showed that enhancing JPH2 expression using a gene-therapy approach after the onset of the disease prevented the progression of heart failure, thereby demonstrating that JPH2 could be a therapeutic target for the treatment of cardiomyopathies associated with T-tubule deterioration." (PMID 32053184, 2021). "Of note, JPH2 has been suggested to anchor transverse but not longitudinal elements of t-tubules, consistent with the observation that decreased JPH2 expression during heart failure is associated with an increasingly longitudinal t-tubule orientation." (PMID 28447290, 2017). "Finally, evidence from skeletal muscle indicates that JPH2 may also play a role in maintaining LTCCs as part of a dyadic protein complex, suggesting that JPH2 reduction during heart failure could have complex effects on both LTCC localization and overall dyadic structure." (PMID 30618792, 2018). "However, in mouse models of heart failure where Jph2 expression is not reduced, augmenting Mg29 expression is of no protective value." (PMID 28706255, 2017). "Interestingly, similar cellular defects were observed in a non-genetic model of pressure overload–induced heart failure, which could be rescued by the overexpression of JPH2." (PMID 38438248, 2024). "Therefore, targeting this miR-24 pathway may not be suitable for therapeutic targeting of JPH2 in the context of heart failure treatment." (PMID 35001666, 2022).
cardiomyopathy (11 papers, 2018 to 2024). A disease of the heart muscle or myocardium proper. "Given the scarcity of knowledge in this area, our main objective was to study how JPH2 variants associated with different types of cardiomyopathies (i.e., HCM and DCM) impact lipid metabolism in the heart." (PMID 38438248, 2024). "The functional consequences of inherited JPH2 variants associated with cardiomyopathy remain incompletely understood." (PMID 38438248, 2024). "Overall, we present a comprehensive analysis of the cardiac lipidome in two different cardiomyopathy disease models caused by pathogenic variants in JPH2." (PMID 38438248, 2024). "While JPH2 variants have been associated with cardiomyopathy and arrhythmias, a small number of studies have linked these variants to perturbed skeletal muscle function in vitro." (PMID 35001666, 2022). "A subset of all JPH2 mutations associated with cardiomyopathies has been functionally characterized in cardiomyocytes or cardiomyocyte-derived cell lines." (PMID 35053257, 2022). "Due to the high background rate of rare variants in JPH2, we explored the rate of pathogenic JPH2 variants found in patients clinically diagnosed with cardiomyopathy." (PMID 31227780, 2019). "This highlights the need for more research to improve identification of susceptibility alleles and the role that missense JPH2 variants play in contributing to cardiomyopathies." (PMID 31227780, 2019). "Our findings add to the growing evidence that variants in JPH2 play a role in cardiomyopathy; and suggest that this novel biallelic truncating variant can give rise to severe, early-onset cardiomyopathy." (PMID 31227780, 2019). "A heterozygous JPH2 c.482C>A, p.(Thr161Lys) (NM_020433.4) variant was observed in nine unrelated Finnish probands with cardiomyopathy." (PMID 30235249, 2018). "Role of the JPH2 in cardiomyopathies has been obscure as only one rare variant segregating with any type of cardiomyopathy has been published." (PMID 30235249, 2018). "Future studies may reveal whether normalization of FA levels could slow the development of JPH2-associated cardiomyopathy." (PMID 38438248, 2024). "Mutations in the JPH2 gene have been associated with several types of cardiomyopathy." (PMID 35001666, 2022). "These interesting results suggest that normalizing JPH2 levels might represent a new therapeutic approach for the treatment of cardiomyopathy associated with frequent PVCs." (PMID 35001666, 2022). "In the heart, remodeling and loss of TT in chronic heart failure, in aging or in cardiomyopathies correlate with downregulation of JPH2 protein expression and/or loss of JPH2 localization at TT; in addition, mutations in JPH2 are linked to the development of cardiomyopathies." (PMID 35454077, 2022). "Taken together, these results suggest that downregulation of JPH2 might be a common mechanism underlying the disruption of T-tubules in cardiomyopathies of different aetiology." (PMID 32053184, 2021). "However, little is known about the significance JPH2 as a causative gene for cardiomyopathy." (PMID 30235249, 2018). "Further research is required to investigate the potential interaction between SORB2 and JPH2 in the context of cardiomyopathy development." (PMID 35001666, 2022). "Several studies have demonstrated that JPH2 protein levels are downregulated in various types of cardiomyopathy, a common type of chronic disease of the heart muscle." (PMID 35001666, 2022). "We have identified the JPH2 p.(Thr161Lys) variant in nine Finnish index patients with HCM and have shown co-segregation of the variant with cardiomyopathy in six of these families." (PMID 30235249, 2018). "Although some JPH2 variants associated with DCM have been identified in patients, such as the truncation variant E641*, little is known about the potential molecular mechanisms that cause cardiomyopathy development." (PMID 38438248, 2024).
cardiomyopathy (continued). "The reduced JPH2 expression levels could be reversed by swimming exercise and silencing of 3-hydroxy-3-methylglutaryl-CoA synthase 2 (HMGCS2), suggesting that the cardiomyopathy development itself led to loss of JPH2." (PMID 35001666, 2022). "Reduced JPH2 expression levels and functional activity may also contribute to atrial fibrillation and premature ventricular contraction-induced cardiomyopathy." (PMID 35001666, 2022). "While such studies have been performed on hiPSCs from patients with HCM, there is currently no such lines with cardiomyopathy-linked JPH2 variants." (PMID 35001666, 2022). "Taken together, these results suggest that pathogenic JPH2 variants are rare among patients with cardiomyopathy and are largely absent in population and clinical WES-based cohorts." (PMID 31227780, 2019). "The importance of JPH2 in the structural and functional integrity of the JMC is further reinforced clinically by the observation of disease-associated variants in JPH2 found in a small number of patients with cardiomyopathy as well as atrial fibrillation." (PMID 31227780, 2019). "A few lncRNAs are located in the introns of cardiomyopathy-related genes (e.g., TTN, ACTC1, TPM1, JPH2, ANKRD1, DTNA, TMPO, and FHL2) or physically close to these genes." (PMID 32344918, 2020).